GREM1 (gremlin 1, DAN family BMP antagonist)
Description:
Cytokine that may play an important role during carcinogenesis and metanephric kidney organogenesis, as a BMP antagonist required for early limb outgrowth and patterning in maintaining the FGF4-SHH feedback loop. Down-regulates the BMP4 signaling in a dose-dependent manner (By similarity). Antagonist of BMP2; inhibits BMP2-mediated differentiation of osteoblasts (in vitro). Acts as inhibitor of monocyte chemotaxis. Can inhibit the growth or viability of normal cells but not transformed cells when is overexpressed (By similarity).
Synonyms: IHG-2; CKTSF1B1; DAND2; DRM; PIG2; gremlin; HMPS; C15DUPq; CRAC1; CRCS4; DUP15q; HMPS1; MPSH
Tractability: Antibody: UniProt places it where antibodies can reach, with high confidence; UniProt predicts a signal peptide or a membrane-spanning region; its Gene Ontology location is reachable by antibodies, with medium confidence. PROTAC: ubiquitination databases record sites on it.
Gene: Protein-coding gene on chromosome 15 (32,716,998 to 32,745,106, forward strand). Ensembl gene ENSG00000166923.
Subcellular location: Secreted
Pathways (Reactome):
Developmental Biology: Formation of the ureteric bud
Gene Ontology:
Molecular function: BMP binding; protein binding; protein homodimerization activity; protein sequestering activity; receptor ligand inhibitor activity; morphogen activity; receptor ligand activity; transmembrane receptor protein tyrosine kinase activator activity; vascular endothelial growth factor receptor 2 binding
Biological process: cell morphogenesis; collagen fibril organization; determination of dorsal identity; limb development; negative regulation of apoptotic process; negative regulation of BMP signaling pathway; negative regulation of bone mineralization; negative regulation of bone mineralization involved in bone maturation; negative regulation of bone remodeling; negative regulation of bone trabecula formation; negative regulation of canonical Wnt signaling pathway; negative regulation of chondrocyte differentiation; negative regulation of osteoblast differentiation; negative regulation of osteoblast proliferation; negative regulation of osteoclast proliferation; negative regulation of SMAD protein signal transduction; positive regulation of cell population proliferation; regulation of epithelial to mesenchymal transition; cardiac muscle cell differentiation; negative regulation of monocyte chemotaxis; positive regulation of cell migration involved in sprouting angiogenesis; positive regulation of receptor internalization; positive regulation of transcription by RNA polymerase II; positive regulation of vascular endothelial growth factor signaling pathway; regulation of stress-activated MAPK cascade; and 12 more
Cellular component: extracellular matrix; extracellular region; cell surface
Genetic constraint (gnomAD): Loss-of-function variants: 6 observed, 13.84 expected, observed/expected ratio (o/e) 0.43, 90% interval 0.24 to 0.86. The upper end of that interval is the gene's LOEUF score, 0.86, which puts it in group 3 of 6, group 1 being the genes least tolerant of losing a copy. Missense variants: 185 observed, 244.4 expected, observed/expected ratio (o/e) 0.76, 90% interval 0.67 to 0.86. Synonymous variants: 98 observed, 98.95 expected, observed/expected ratio (o/e) 0.99, 90% interval 0.84 to 1.17.
Gene-disease validity (ClinGen):
ClinGen rates the evidence that GREM1 causes each of these diseases.
hereditary mixed polyposis syndrome (autosomal dominant): Definitive.
Homologues: Orthologues: macaque GREM1 (100% identical), pig GREM1 (100% identical), dog GREM1 (99% identical), rabbit GREM1 (99% identical), guinea pig GREM1 (99% identical), rat Grem1 (98% identical), mouse Grem1 (98% identical), tropical clawed frog grem1 (82% identical), zebrafish grem1b (67% identical), zebrafish grem1a (59% identical), Caenorhabditis elegans F35B12.10 (27% identical). Paralogues in human: GREM2 (52% identical), NBL1 (21% identical).
Diseases named in the same sentence as GREM1 in open-access papers:
GREM1 is named in the same sentence as 233 diseases in open-access papers, as found by Europe PMC text mining. Sharing a sentence is not in itself a finding about the gene and the disease. The quoted sentences say what the papers report.
colorectal cancer (42 papers, 2011 to 2025). A primary or metastatic malignant neoplasm that affects the colon or rectum. "In sporadic colorectal cancer, high stromal GREM1 expression is clearly associated with aggressive mesenchymal subtypes and poor prognosis." (PMID 40467544, 2025). "Among the significant findings, was GREM1, which manifested significant (p-value < 1×10−05) pQTS association with colorectal cancer in both EA and AA, primarily driven by cis-variants." (PMID 41358317, 2025). "Overexpression of Grem1 has been associated with various cancers, including colorectal cancer (CRC)." (PMID 39149516, 2024). "Using data from three large international consortia, this study discovered a locus in the FMN1/GREM1 gene region that interacts with BMI on the association with colorectal cancer risk." (PMID 37249599, 2023). "In the two-step EDGE approach, we observed a statistically significant interaction between variants located in the formin 1/Gremlin 1 (FMN1/GREM1) gene region and BMI in colorectal cancer risk." (PMID 37249599, 2023). "In conclusion, we identified a new locus in the FMN1/GREM1 gene region that interacts with BMI on the association with colorectal cancer risk." (PMID 37249599, 2023). "This gene-environment interaction analysis revealed a genetic locus in FMN1/GREM1 that interacts with body mass index in colorectal cancer risk, suggesting potential implications for precision prevention strategies." (PMID 37249599, 2023). "In this study from three large international colorectal cancer consortia, we discovered a new locus located within the FMN1/GREM1 gene region (rs58349661) that interacts with BMI on the association with colorectal cancer risk." (PMID 37249599, 2023). "Our novel G×BMI finding at the FMN1/GREM1 locus is close to a region with multiple known GWAS loci for colorectal cancer risk." (PMID 37249599, 2023). "Overexpression of GREM1 in lung and colorectal cancers, as well as malignant mesothelioma, is associated with disease progression by promoting cell survival, proliferation, and invasion in vitro." (PMID 32756430, 2020). "Stromal Gremlin expression in colorectal cancer, as determined by GREM1 in situ hybridization, was found to be associated with a less advanced cancer stage, decreased lymphovascular invasion and improved recurrence-free and overall survival." (PMID 32486027, 2020). "Consistently, GREM1 overexpression has been linked to a range of cancers, including colorectal cancer (CRC), with mutations affecting BMP signalling occurring in a large number of CRCs." (PMID 31384391, 2019). "Although GREM1 might promote carcinogenesis, its expression has also been shown to be associated with a good prognosis in gastric and colorectal cancers." (PMID 31024927, 2019). "Interestingly, GREM1 has been previously related with a locus strongly associated with increased colorectal cancer risk." (PMID 25253512, 2014). "Furthermore, Li and colleagues have indicated that hsa-miR-185-3p regulated the expression of GREM1 via binding to the miR-185-3p, which could promote the colorectal cancer risk." (PMID 35330456, 2022). "Transcenta have developed TST003, a neutralizing GREM1 antibody that is currently in Phase 1 clinical trials, to test safety and pharmacodynamics in colorectal cancer patients with locally advanced or solid tumors." (PMID 40277903, 2025). "Binding of GREM1-FITC to HCT116 colorectal cancer epithelial cell membranes became evident between 5 and 15 min, with a ring-like membrane-bound pattern evident at 60 min." (PMID 41033552, 2025). "We report that GREM1 is secreted, binds to, and is endocytosed in colorectal cancer cells, a process that requires BMP binding." (PMID 41033552, 2025).
colorectal cancer (continued). "GREM1 mRNA was detected in the cancer invasion front in a model of colorectal cancer, contributing to cancer cell motility." (PMID 40277903, 2025). "The analysis of data from the TIME database revealed a positive correlation between GREM1 expression in colorectal cancer tissues and M1 polarization of macrophages, as well as a negative correlation with macrophage M2 polarization." (PMID 38970064, 2024). "Nevertheless, the role of miR-455 in regulating GREM1 in colorectal cancer liver metastases and how miR-455/GREM1 axis influences tumour immune microenvironment is unclear." (PMID 38970064, 2024). "miR-455/GREM1 axis promotes colorectal cancer cells proliferation, migration, invasion via affected PI3K/AKT pathway." (PMID 38970064, 2024). "Some studies have found that the high expression of GREM1 in intestinal epithelial cells can promote the occurrence of precancerous lesions of colorectal cancer." (PMID 38970064, 2024). "In order to investigate the influence of miR-455/GREM1 axis on the progression and metastasis of colorectal cancer, we used miR-455 mimic and GREM1 overexpression plasmids to study in vitro." (PMID 38970064, 2024). "In vivo, colorectal cancer liver metastasis(CRLM) model mice was established to inquiry the effect of miR-455/GREM1 axis on tumor growth and macrophage polarization." (PMID 38970064, 2024). "To verify the binding of miR-455 to 3 ‘-UTR of GREM1 mRNA, we co-transfected miR-455 mimic with GREM1 wild-type 3’-UTR or GREM1 mutant 3’-UTR in human colorectal cancer cells, and then measured and calculated luciferase ability." (PMID 38970064, 2024). "Our results illustrate that knocking down GREM1 can promote the proliferation and migration of colorectal cancer cells." (PMID 38970064, 2024). "Our study found that miR-455 increased expression in hepatic metastases of colorectal cancer and promoted the growth and migration of colorectal cancer cells by targeting GREM1." (PMID 38970064, 2024). "In this study, we investigated the role of Gremlin-1 (GREM1), a secreted protein, in the invasion and metastasis of colorectal cancer (CRC) cells in vitro and in vivo." (PMID 35883579, 2022). "The role of SCG5 in colorectal cancer has not been well characterized, while much is known about its neighbor GREM1’s role in colorectal cancer." (PMID 33976257, 2021). "It has also been shown that SNPs near GREM1 and SCG5 are significantly related to increased risk of colorectal cancer (CRC)." (PMID 33962391, 2021). "This work helps characterize the relationship between variants in the SCL22A3, SCG5, GREM1, and STXBP5-AS1 genes and colorectal cancer in a diverse Indonesian population." (PMID 33976257, 2021). "Previous studies have identified that stage II colorectal cancer (CRC) patients with high levels of GREM1 gene expression in their tumour tissue have a poorer prognosis." (PMID 31384391, 2019). "It was recently shown that GREM1 can be produced by cancer-associated fibroblasts (CAFs) in breast cancer patients and that CAFs are the main source of GREM1 in colorectal cancer tissue." (PMID 31694641, 2019). "For example, Grem1 expression correlates with progression-free survival in pancreatic neuroendocrine tumors and colorectal cancer, but it is an indicator of poor progression-free survival in cervical cancer." (PMID 31533776, 2019). "GREM1 was also detected at the colorectal cancer desmoplastic invasion front, highlighting a potential role in cancer metastasis." (PMID 31533776, 2019). "b GREM1 expression in epithelial cells, leukocytes, fibroblasts and endothelial cells in colorectal cancer dataset GSE39396." (PMID 31533776, 2019).
colorectal cancer (continued). "However, a small number of papers argue the opposite and suggest that high levels of GREM1 are prognostic of less aggressive tumor phenotypes and improved patient outcomes in both pancreatic adenocarcinoma and colorectal cancer." (PMID 41033552, 2025). "miR-455 and GREM1 are important factors in the process of liver metastasis of colorectal cancer." (PMID 38970064, 2024). "In vivo, Deletion of GREM1 can promote the occurrence of liver metastasis of colorectal cancer." (PMID 38970064, 2024). "Collectively, our findings suggest that low expression of GREM1 may contribute to the progression and metastasis of colorectal cancer via the PI3K/AKT pathway and by influencing macrophage polarization." (PMID 38970064, 2024). "Therefore, we believe that miR-455 targets GREM1 to promote the proliferation and migration of colorectal cancer cells." (PMID 38970064, 2024). "Additionally, the GREM1 gene is amplified in a rare autosomal dominant inherited form of colorectal cancer." (PMID 37615860, 2023). "Other groups identified increased Grem1 mRNA expression in myCAFs in basal cell carcinoma, suggesting that this hypothesis extends beyond colorectal cancer." (PMID 37615860, 2023). "Mutations in GREM1 are associated with the development of hereditary mixed polyposis syndrome (HMPS), a rare condition associated with an increased development of colon polyps and higher colorectal cancer risk, often beginning in childhood." (PMID 37249599, 2023). "Taken together, our results demonstrate that GREM1 is an invasion-promoting factor via regulation of ATF6 and ATF4 expression in CRC cells, suggesting GREM1 may be a potential pharmacological target for colorectal cancer treatment." (PMID 35883579, 2022). "Therefore, rs12915554 potentially enhanced colorectal cancer through modulating the relative expression of the GREM1 gene via impairment of miR-185-3p binding site." (PMID 35330456, 2022). "Interestingly, seven of the shared significant genes have been associated to colorectal cancers, including UTP23, GREM1, SCG5, SMAD7, CABLES2, LAMA5, and PREX1." (PMID 32245788, 2020). "Moreover, the recent advances in molecular techniques, in particular Next-Generation Sequencing, have led to the identification of many new genes involved in the predisposition to colorectal cancers, such as RPS20, POLE, POLD1, AXIN2, NTHL1, MSH3, RNF43 and GREM1." (PMID 36768460, 2023). "It is possible that FMN1 acts in tandem with neighboring genes, such as GREM1 and SCG5 because the catena SCG5-GREM1-FMN1 constitutes a hotspot for several colorectal cancer–related SNPs." (PMID 37249599, 2023). "The authors showed the presence of GREM1-positive CAFs and immunoglobulin superfamily containing leucine-rich repeats (ISLR) (also known as Meflin)-positive CAFs in colorectal cancer." (PMID 37615860, 2023). "GREM1 as functionally opposing BMP signaling pathway gene, was confirmed to promote the advancement and progression of colorectal cancer." (PMID 36601127, 2022). "The role of GREM1 in carcinogenesis and development of colorectal cancer is still vague, and the mechanism of GREM1 in liver metastasis of colorectal cancer has not been reported." (PMID 38970064, 2024). "For investigate the expression of miR-455、GREM1 and BMP6 in colorectal cancer, we collected LM tissues, PT tissues and PC tissues of colorectal cancer of 5 patients for qRT-PCR and western blotting detection from the First Affiliated Hospital of Nanjing Medical University." (PMID 38970064, 2024).
colorectal cancer (continued). "Knocking down GREM1 activates PI3K/AKT phosphorylation and promotes macrophage M2 polarization by increasing BMP6 expression, thus promoting the proliferation and migration of colorectal cancer in vitro and promoting the occurrence of liver metastasis of colorectal cancer in vivo." (PMID 38970064, 2024).
breast carcinoma (41 papers, 2011 to 2025). "In breast cancer, GREM1 is secreted by cancer-associated fibroblasts (CAFs) and promotes an immunosuppressive tumor microenvironment, facilitating tumor invasion and metastasis." (PMID 40066442, 2025). "Some well‐studied BMP antagonists include Noggin, which has been implicated in promoting skin and breast cancer tumorigenesis, and the Gremlins (GREM1 and 2), with repression of GREM1 shown to inhibit tumour cell proliferation." (PMID 40434957, 2025). "GREM1 plays an important role in the growth of breast cancer cells and is associated with poor survival of breast cancer patients." (PMID 33287358, 2020). "Our present study demonstrates that GREM1 plays an important role in the growth of breast cancer cells, and the persistent upregulation of GREM1 is associated with poor prognosis in breast cancer patients." (PMID 32572171, 2020). "The GREM1 expression in breast cancer tissue samples is thus mainly caused by the presence of tumor stroma." (PMID 31533776, 2019). "Although we found an association between Grem1 and poor breast cancer prognosis, the prognostic significance of Grem1 in different cancer types is not consistent." (PMID 31533776, 2019). "The role of Grem1 in breast cancer-associated fibroblast (CAF) activation was measured by analyzing the expression of fibroblast markers, phalloidin staining, and collagen contraction assays." (PMID 31533776, 2019). "GREM1 overexpression was associated with metastasis in breast cancer and was associated with poorer patient prognosis, GREM1 expression was detected in cancer-associated fibroblasts (CAFs) promoting breast cancer extravasation in a Zebrafish model." (PMID 40277903, 2025). "Additionally, higher GREM1 expression in cancer-associated fibroblasts (CAFs) was postulated to create a favourable desmoplastic niche for the invasion of breast cancer cells." (PMID 37615860, 2023). "However, the role of GREM1 in metastasis of breast cancer cells and its underlying mechanisms remain poorly understood." (PMID 33287358, 2020). "More recently, it has been reported that GREM1 is associated with breast cancer metastasis in vivo." (PMID 33287358, 2020). "To explore underlying mechanisms by which GREM1 could enhance the metastasis of breast cancer cells, we first screened representative MMPs in GREM1-depleted or GREM1-overexpressing breast cancer cells." (PMID 33287358, 2020). "In addition, GREM1 is associated with metastasis of breast cancer cells." (PMID 33287358, 2020). "Based on our findings that elevated BMP expression does not correlate with reduced RFS, whereas high GREM1 expression is associated with poor prognosis in breast cancer, we hypothesized that combining the expression levels of BMPs and GREM1 annuls the observed correlation of GREM1 with RFS." (PMID 31694641, 2019). "For instance, in breast cancer, GREM1 acts as a BMP antagonist to inhibit the BMP/SMAD signaling pathway, thereby promoting EMT and tumor invasion." (PMID 40066442, 2025). "Since ex.50.T can bind BC-derived EVs in a GREM1-dependent manner, we investigated its potential to inhibit EV-mediated crosstalk between BC cells and NFs, the major component of the breast cancer TME." (PMID 40069570, 2025). "GREM1 is an essential factor in the reciprocal interplay between breast cancer cells and CAF, which expedites cancer cell invasion." (PMID 40849639, 2025). "Altogether, our findings highlight ex.50.T as a novel therapeutical avenue for breast cancer and potentially other GREM1-dependent malignancies, offering insights into disrupting TME dynamics and enhancing cancer treatment strategies." (PMID 40069570, 2025). "This is different from the conventional findings that gremlin-1 (GREM1) can facilitate breast cancer pulmonary metastasis via a signal transducer and activator of transcription (STAT) 3-mediated MMP13 regulation." (PMID 40243781, 2025).